U2AF1L4 (U2 small nuclear RNA auxiliary factor 1 like 4)
Description:
RNA-binding protein that function as a pre-mRNA splicing factor. Plays a critical role in both constitutive and enhancer-dependent splicing by mediating protein-protein interactions and protein-RNA interactions required for accurate 3'-splice site selection. Acts by enhancing the binding of U2AF2 to weak pyrimidine tracts. Also participates in the regulation of alternative pre-mRNA splicing. Activates exon 5 skipping of PTPRC during T-cell activation; an event reversed by GFI1. Binds to RNA at the AG dinucleotide at the 3'-splice site (By similarity). Shows a preference for AGC or AGA (By similarity).
Synonyms: U2AF1-RS3; U2AF1L3; MGC33901; U2af26; U2AF1L3V1; U2AF1RS3
Tractability: PROTAC: ubiquitination databases record sites on it; its protein half-life has been measured.
Gene: Protein-coding gene on chromosome 19 (35,742,464 to 35,745,445, reverse strand). Ensembl gene ENSG00000161265.
Subcellular location: Nucleus; Nucleus speckle; Cytoplasm
Subcellular location (Human Protein Atlas): Nucleoplasm
Pathways (Reactome):
Metabolism of RNA: Transport of Mature mRNA derived from an Intron-Containing Transcript; mRNA 3'-end processing; mRNA Polyadenylation; mRNA Splicing - Major Pathway
Disease: Dengue Virus-Host Interactions
Gene Ontology:
Molecular function: pre-mRNA 3'-splice site binding; metal ion binding; nucleic acid binding; RNA binding
Biological process: mRNA splicing, via spliceosome
Cellular component: nucleoplasm; spliceosomal complex; U2AF complex; cytoplasm; nuclear speck; nucleus
Genetic constraint (gnomAD): Loss-of-function variants: 22 observed, 24.08 expected, observed/expected ratio (o/e) 0.91, 90% interval 0.65 to 1.3. The upper end of that interval is the gene's LOEUF score, 1.3, which puts it in group 5 of 6, group 1 being the genes least tolerant of losing a copy. Missense variants: 259 observed, 259.45 expected, observed/expected ratio (o/e) 1, 90% interval 0.9 to 1.11. Synonymous variants: 92 observed, 95.26 expected, observed/expected ratio (o/e) 0.97, 90% interval 0.81 to 1.15.
Homologues: Orthologues: chimpanzee U2AF1L4 (98% identical), dog U2AF1L4 (94% identical), mouse U2af1l4 (93% identical), pig U2AF1L4 (93% identical), macaque U2AF1L4 (89% identical), rat U2af1l4 (76% identical), Drosophila melanogaster U2af38 (73% identical), Caenorhabditis elegans uaf-2 (61% identical). Paralogues in human: U2AF1 (79% identical), ZRSR2 (39% identical).
Diseases named in the same sentence as U2AF1L4 in open-access papers:
U2AF1L4 is named in the same sentence as 12 diseases in open-access papers, as found by Europe PMC text mining. Sharing a sentence is not in itself a finding about the gene and the disease. The quoted sentences say what the papers report.
renal carcinoma (1 paper, 2023). A carcinoma arising from the epithelium of the renal parenchyma or the renal pelvis. "In bioinformatics studies of other related tumors, it was found that U2AF1L4 a prognostic factor for renal cancer, especially renal clear cell carcinoma." (PMID 37396042, 2023).
renal clear cell carcinoma (1 paper, 2023). "U2AF1L4 was reported to be involved in renal clear cell carcinoma, but there is a lack of corresponding mechanism research." (PMID 37396042, 2023).
U2AF1L4 also shares sentences with these, for which no sentence is quoted: cancer (1 paper); Charcot-Marie-Tooth disease (1); Diarrhea (1); Fundus dystrophy (1); Immunodeficiency (1); nemaline myopathy (1); nephronophthisis (1); nephrotic syndrome (1); non-syndromic intellectual disability (1); rheumatoid arthritis (1).